CCND1 (cyclin D1)
Diseases named in the same sentence as CCND1 in open-access papers (continued):
Sharing a sentence is not in itself a finding about the gene and the disease.
tumor (continued). "Our findings support this, demonstrating that NEIL3 overexpression increases β-catenin and cyclin D1 levels, potentially promoting cell proliferation and tumor growth." (PMID 39910812, 2025). "ZFP36L1, an RNA-binding protein, suppresses the cell cycle by degrading mRNAs such as Cyclin D1, thereby exerting tumor-suppressive effects." (PMID 41315466, 2025). "Elevated CCND1 expression was observed in tumor tissues (T1, T32, T35, T46, and T52) compared to their corresponding peritumoral tissues (p = 0.02213), as illustrated in the box plot." (PMID 40344393, 2025). "It is also well known that NF-κB has direct connections to the regulation of Bcl-2 and Cyclin D1 expression to desensitize tumor cells, including in GBM." (PMID 40564997, 2025). "miR-184 was also found to be downregulated in ccRCC tissues and directly targeted Cyclin D1 (CCND1), a key regulator of the cell cycle, further confirming its tumour-suppressive function." (PMID 41379397, 2025). "Similar results were obtained for the content of E-cadherin, cyclin D1, and immunosuppressive interleukin 17 in tumor cells, which is able to reduce the activity of T-killer cells in the tumor." (PMID 40283189, 2025). "CDK4/6 inhibitors, such as palbociclib, are promising anti-tumor agents, but easily resulted in resistance due to the overexpression of CCND1 and CCNE." (PMID 41271634, 2025). "When co-infected, F.n. and P.g. increased invasion, proliferation and tumor size, with marked upregulation of cyclin D1." (PMID 40924302, 2025). "Cyclin D1 has been found to be overexpressed in CRC tumor samples, but meta-analyses revealed uncertain results." (PMID 41008614, 2025). "Elevation of CCND1 protein levels can activate the CCND1–CDK4/6–pRB–E2F signaling cascade which in turn promotes the transcription of E2F target genes that promote tumor growth." (PMID 41081939, 2025). "Immunohistochemistry staining of tumour sections showed an increase in the levels of pSTAT3 and cyclin D1 in IL‐11‐treated mice." (PMID 40673604, 2025). "Similar to aSCLC, CCND1, CDK4, and MDM2 are among the most common amplifications associated with chromothripsis across tumor type." (PMID 39185963, 2025). "Significant correlations were observed between Cyclin D1 expression and tumor site, local recurrence, distant metastasis, and lymph node involvement." (PMID 41189865, 2025). "5‐HT1BR activated by 5‐HT activates the MAPK/ERK pathway, EF‐2 kinase, the cyclin D1 pathway and α‐smooth muscle antigen; inhibits the caspase pathway; and inhibits apoptosis in tumor cells." (PMID 40937192, 2025). "On the other hand, the RNA helicase DDX5 stabilized the CCND1 mRNA by binding to the common stem–loop structure and promoted its expression and tumor cell cycle progression." (PMID 41263459, 2025). "Consistently, IHC detection of tumor xenografts showed that the levels of β-catenin, c-Myc, and Cyclin D1 were significantly reduced in the mice administered SM compared to those treated with vehicle." (PMID 40646619, 2025). "This process results in the acetylation of H3 at Lys9 and the EGF-triggered transcription of cyclin D1 and c-Myc, which in turn enhances cyclin D1-driven cell cycle progression and tumor formation." (PMID 40057191, 2025).
tumor (continued). "In line with this, RT-qPCR analysis demonstrated that knockdown of PSMB8 or TMZ treatment dramatically reduced the expression of c-Myc and cyclin D1 (tumor growth markers) and enhanced caspase- 3 (tumor apoptosis marker)." (PMID 40335825, 2025). "Parafibromin functions as a tumor suppressor by inducing apoptosis and inhibiting cell cycle-its absence results in overexpression of Cyclin D1." (PMID 40038693, 2025). "As the first substrate of AKT, GSK3β is involved in tumor formation and progression and acts as a tumor suppressor because its activation accelerates the degradation of oncogenes such as cyclin D1 and c-Myc." (PMID 40814339, 2025). "CCND1 is believed to be an oncogene that accelerates G1/S transformation, thus leading to uncontrolled cell proliferation and tumour progression." (PMID 40852585, 2025). "This suppression results in reduced translation of oncogenic proteins such as cyclin D1 and c‐Myc, preventing tumor cell proliferation." (PMID 40387523, 2025). "To study a possible association between Fusobacterium and cancer cell proliferation, we analyzed the expression levels of cyclin D1 and c-myc in tumor tissues relative to other tissue types, including tissue from AC, TU, NN, and CS." (PMID 40895532, 2025). "Tob knockdown in human breast carcinoma cell line MCF-7 promotes tumor growth in mouse xenograft models because cyclin D1 is dysregulated." (PMID 40169858, 2025). "The alterations in CELF1 expression also impact the expressions of cyclin D1 and c-Myc, thereby implying a consequential modification in the occurrence, invasion, and metastasis processes within tumor tissues." (PMID 41306913, 2025). "A previous paper reported that inhibiting SIRT1, an NAD+-dependent enzyme, induces cyclin D1 downregulation and suppresses tumor growth in HCC cells." (PMID 39940750, 2025). "For example, CCND1 is well-known for its role in cell cycle G1/S transition and contributes to tumor development." (PMID 40478912, 2025). "They found that circMYLK was highly expressed in LSCC and promoted tumor progression by sequestering miR-195, thereby enhancing cyclin D1 expression and facilitating cell cycle progression." (PMID 39941323, 2025). "These bacteria upregulate cyclin D1, promote hyperplasia, and alter inflammatory and metabolic pathways, contributing to a tumor-permissive environment." (PMID 40924302, 2025). "Considering all the data cited, it has been proposed that, although the total expression of CCND1 is more abundant in normal tissues and concentrated in the cytoplasm, CCND1 in tumor cells is more likely to be transported and accumulated in the nucleus." (PMID 40304827, 2025). "Luteolin-7-O-β-D-glucoside, present at 5.27% in the BESD and 4.64% in the BF1SD, inhibits tumor proliferation by blocking the activation of the NF-κB transcription factor and modulating cyclin D1 expression, thereby slowing cell cycle progression." (PMID 40942095, 2025).
tumor (continued). "Similar to the effect on Cyclin D1 mRNA expression, a dramatic decrease in Cyclin D1 protein was observed, correlating well with the observed antiproliferative effect of 15 and 38 on tumor cells." (PMID 40651614, 2025). "When APC is mutated, β-catenin dissociates from APC, activating the expression of oncogenes like c-myc and cyclin D1, thereby promoting tumor cell growth." (PMID 40641920, 2025). "PT2385 inhibited the expression of HIF-2α-dependent genes associated with tumor growth, including VEGF-A, PAI-1, and Cyclin D1 in ccRCC cell lines, and induced tumor regression in xenograft models." (PMID 40806229, 2025). "Meanwhile, 66CTG overexpression in xenograft tumor tissues enhanced the c-Myc and Cyclin D1 expression levels." (PMID 40628713, 2025). "For instance, at 11q13.3, the risk variant rs10908176 is linked to enhanced CCND1 expression via EPAS1 binding, which is a feature in both normal and tumour cells but amplified in RCC under hypoxic conditions." (PMID 41326661, 2025). "Cyclin D1 not only stimulates tumor growth but also helps cancer cells to evade apoptosis and weaken immune control through its interaction with several other molecular signaling pathways, including B-cell receptor (BCR) and phosphoinositide 3-kinase (PI3K)." (PMID 40002289, 2025). "This cascade ultimately enhances the transcription of genes associated with cell cycle progression, such as cyclin D1, c‐Myc, c‐Fos, c‐Jun, Elk‐1, and cAMP‐response element binding protein (CREB), thereby contributing to increased tumor cell proliferation." (PMID 40387523, 2025). "In vivo experiments further confirmed that X26nt accelerated the expression of CCND1 and tumor growth." (PMID 40697992, 2025). "Now, in addition to our previously reported MOA of OTI-611, we have uncovered OTI-611’s effects on Cyclin D1 and Ki-67 expression, its induction of G1 cell cycle arrest, and its ability to reduce tumor cell proliferation." (PMID 40072047, 2025). "Transcriptional coordination of cellular myelocytomatosis (C-MYC) with Cyclin D1 was reported to accelerate tumor formation and make the tumor progress into a more aggressive phenotype." (PMID 40224178, 2025). "Amplifications or translocations at the CCND1 locus result in its overexpression, leading to dysregulated cell cycle progression, increased cellular proliferation, and enhanced tumor aggressiveness." (PMID 40427514, 2025). "Compared to the treatment with a carnosine solution, the use of pegylated liquisomes showed a higher anticancer activity (decreased tumor growth and cyclin D1 and VEGF levels; increased caspase 3 level)." (PMID 41301028, 2025). "This, in turn, drives the transcriptional activation of Cyclin D1, a cyclin-dependent kinase regulator that promotes the G1-S phase transition in the cell cycle, thereby facilitating tumor growth." (PMID 40307756, 2025). "In parallel, these pathogens affect proliferation via modulation of cyclin D1, p21, and p27, although outcomes vary, ranging from apoptosis to proliferation, depending on strain, bacterial viability, and type of tumor cells." (PMID 40924302, 2025). "Since 72 h, tumor increment was surveyed in HT-29 cells treated by hAMSCs through the EGFR/c-Src/IRSp53/p-AKT/p-Stat3/cyclin D1 signaling cascade." (PMID 41200137, 2025). "Clinically, high circFOXK2 expression is positively correlated with CCND1 levels in both ER-positive breast cancer cell lines and patient tumor tissues." (PMID 40233410, 2025). "Specifically, PHB2 upregulates Cyclin D1 and Cyclin E, facilitating G1/S phase transition and promoting uncontrolled tumor cell proliferation." (PMID 40076502, 2025). "This miRNA cluster operates as a canonical tumor-suppressive axis by targeting genes associated with proliferation and EMT, such as BCL2, CCND1, and VEGFA." (PMID 41303609, 2025). "The Tumor-0 subcluster comprised the majority of cells, with upregulated genes typical of tumor markers, such as Ccnd1, Cd44, Krt7 and Plau." (PMID 41332581, 2025).
tumor (continued). "An in vivo study also demonstrated CDH17 silencing redistributed β-catenin to the cytoplasm, reduced cyclin D1 levels, and increased Rb in tumour tissues." (PMID 41155133, 2025). "We assessed PLK4, PHOX2B, CXCR4, and cyclin D1 expression by IHC in tumor tissues from the same patients exhibiting variable differentiation status." (PMID 40860200, 2025). "C-MYC, a transcription factor, acts as an upstream activator of Cyclin D1, promoting tumor progression by accelerating the cell cycle and enhancing cell proliferation." (PMID 40224178, 2025). "The SMAD4/C-MYC/Cyclin D1 axis plays a pivotal role in regulating key aspects of cancer biology, particularly in the context of cell cycle progression, proliferation, and tumor growth." (PMID 40224178, 2025). "Specifically, VDR downregulates the expression of β-catenin, cyclin D1 and LEF-1 in vitro, and xenografts established by VDR-overexpressing SW480 cells shows suppression of tumor growth and decreased expression of β-catenin, cyclin D1 and LEF-1." (PMID 40630116, 2025). "This peptide enhanced the transcription of Cyclin D1 by stabilizing c-Myc, thereby promoting cell proliferation and the tumor growth of TNBC." (PMID 40628713, 2025). "The RT-qPCR and/or IHC analysis of tumor tissues revealed that ASO-circFOXK2 treatment restored the responses of CCND1 expression, RB phosphorylation, the expression of circFOXK2-regulated E2F target genes, and Ki67 expression to tamoxifen treatment." (PMID 40233410, 2025). "Tumor cells are reactive to smooth muscle actin (SMA), beta-catenin, lymphoid enhancer-binding factor 1 (LEF1), and cyclin D1, and it is associated with catenin beta-1 (CTNNB1) mutation." (PMID 41246587, 2025). "Most studies observed elevated CCND1 levels in advanced-stage tumors, supporting its potential role in promoting tumor progression through increased proliferative signaling and survival mechanisms." (PMID 39940659, 2025). "CD99 and LEF1 inversely correlated with tumor size and proliferative activity (Ki-67), whereas Cyclin D1 and Ki-67 positively correlated with tumor size and lymphovascular invasion (LVI)." (PMID 40307756, 2025). "In ERα-positive tumors, ERβ reportedly suppresses cell growth, forming a heterodimer with ERα and inhibiting its tumor-promoting effect or suppressing the transcription of the c-myc, cyclin D1, or cyclin A genes." (PMID 41373615, 2025). "This synergy depends on viral replication and high cyclin D1 levels in tumor cells, amplifying inhibition of cyclin D1 levels in tumour and VEGF to enhance treatment efficacy." (PMID 40927720, 2025). "Treatment with SB203580 and si‐p38MAPK before the addition of CVB‐D promoted anti‐tumor phenotypes and reduced the expression of Cyclin D1, Snail, and p62." (PMID 40416597, 2025). "Collectively, our findings elucidated a novel tumor-suppressive role of PPP1R12B in HCC through modulation of the PAK2/β-catenin/Cyclin D1 axis." (PMID 40612101, 2025). "Akt1 is primarily responsible for the proliferative potential of cells by upregulating Cyclin D1 and S6 and is more highly expressed in the primary BC tumor sample from the breast." (PMID 40080721, 2025). "Upon activation of the IL-6/JAK/STAT3 signaling pathway, the expression of genes such as Cyclin D1 and Bcl-2 is upregulated, promoting tumor cell cycle progression and inhibiting apoptosis, thereby enhancing tumor cell proliferation and survival." (PMID 40909292, 2025).
tumor (continued). "In this study, our results suggest that M1 exos, enriched with miR-20b, regulate the DNA damage repair pathway in tumor cells by targeting CCND1, enhancing the radiosensitivity of HPV+ HNSCC." (PMID 41395621, 2025). "APC regulates cell growth, and prevents tumor formation by modulating the Wnt signaling pathway, whose activation leads to the transcription of genes involved in tumorigenesis such as cyclin D1 (CCND1) and c-MYC." (PMID 40943367, 2025). "These nano-micelles, at concentrations of 0.31–80 mg/mL, inhibited cell growth and invasion, induced tumor shrinkage, and triggered apoptosis by downregulating key signaling molecules like NF-κB, IκB, cyclin D1, survivin, axin, and E-cadherin." (PMID 39861761, 2025). "Specifically, ASBP-AH3 reduces SKP2 and cyclin D1 levels while upregulating p21, thereby disrupting the cell cycle and suppressing tumor growth." (PMID 40004973, 2025). "In cytotrophoblastoma, the mesenchymal-epithelial transition factor (C-MET) promotes PKM2 nuclear translocation via ERK1/2 phosphorylation, where it interacts with histone H3 to upregulate CCND1 and c-Myc, ultimately driving tumor proliferation and growth." (PMID 41169372, 2025). "Further, Cyclin D1 expression was found to be overexpressed in the basal and parabasal layers in non-tumor epithelium adjacent to OSCC." (PMID 41465166, 2025). "By directly acting on the Cyclin D1 promoter region, c-Myc promotes Cyclin D1 transcription, thereby influencing tumor cell proliferation." (PMID 40936898, 2025). "ZNF306, a member of the BTB/POZ subfamily in the ZNF family, is often regarded as a tumor suppressor and can bind to the promoter region of the CCND1 gene in CRC tissues, thereby inhibiting the expression of cytosolic Cyclin D1." (PMID 40085529, 2025). "Although aggressive tumor features are linked to high expression of Ki‐67, PCNA, PHH3, and cyclin D1, their independence as prognostic markers frequently depends on the particular context and patient group." (PMID 40051490, 2025). "The inhibition of CCND1 renders tumor cells more sensitive to temozolomide (TMZ) treatment and temozolomide-induced apoptosis." (PMID 39940838, 2025). "QKI stabilization of CCND1 in tumor ECs in turn promoted tumor EC proliferation, tumor angiogenesis and metastases." (PMID 41222726, 2025). "Taken together, these studies support the notion that HACE1 exerts a tumor suppressor function by regulating cyclin D1." (PMID 40948788, 2025). "In DLBCL, overexpression of GPNMB promotes nuclear translocation of β-catenin by targeting YAP1, thereby enhancing the transcription of cyclin D1 and c-Myc, which in turn accelerates tumor proliferation." (PMID 41189944, 2025). "We showed the suppressive effect of ASPH inhibitors on cyclin D1 expression, c-myc phosphorylation, and the transition from G1 to S phase in the examined tumor cell lines." (PMID 38817852, 2024). "Of these, Cyclin D1 induces the transition from the G1 to S phase through complex formation with Cdk4 and Cdk, leading to tumour growth." (PMID 38612399, 2024). "Late first childbirth was significantly related to lobular type tumours, grade III tumours, high levels of cyclin D1, and low levels of p27." (PMID 39096427, 2024).